INTS6L (integrator complex subunit 6 like)
Synonyms: DDX26B; FLJ41215
Tractability: PROTAC: ubiquitination databases record sites on it.
Gene: Protein-coding gene on chromosome X (135,520,622 to 135,582,534, forward strand). Ensembl gene ENSG00000165359.
Subcellular location (Human Protein Atlas): Centrosome; Mitochondria; Nuclear bodies
Gene Ontology:
Molecular function: protein-macromolecule adaptor activity
Biological process: snRNA 3'-end processing
Cellular component: centrosome; integrator complex
Homologues: Orthologues: chimpanzee INTS6L (99% identical), macaque INTS6L (98% identical), pig INTS6L (92% identical), rat Ints6l (92% identical), dog INTS6L (89% identical), guinea pig INTS6L (88% identical), mouse Ints6l (87% identical), rabbit INTS6L (86% identical), tropical clawed frog ints6l (77% identical), zebrafish ints6l (71% identical), Drosophila melanogaster IntS6 (39% identical), Caenorhabditis elegans ints-6 (25% identical). Paralogues in human: INTS6 (68% identical), SAGE1 (17% identical), CT45A10 (7% identical), CT45A2 (7% identical), CT45A8 (7% identical), CT45A9 (7% identical), CT45A5 (7% identical), CT45A6 (7% identical), CT45A7 (7% identical), CT45A3 (6% identical), CT45A1 (6% identical).
Diseases named in the same sentence as INTS6L in open-access papers:
INTS6L is named in the same sentence as 6 diseases in open-access papers, as found by Europe PMC text mining. Sharing a sentence is not in itself a finding about the gene and the disease. The quoted sentences say what the papers report.
breast carcinoma (2 papers, 2011 to 2017). "Our analysis reveals that among these genes, INTS6L is significantly down-modulated in breast cancer (logFC = −1.75; FDR = 1.47 × 10−21)." (PMID 28468258, 2017).
cardiomyopathy (1 paper, 2022). A disease of the heart muscle or myocardium proper. "Ints6l is a gene with limited information, almost no functional annotation and no known disease association before our identification of a heart phenotype consistent with cardiomyopathy." (PMID 39195995, 2022).
INTS6L also shares sentences with these, for which no sentence is quoted: autism (1 paper); hypertrophic cardiomyopathy (1); neurodevelopmental disorder (1); tumor (1).